DAPK1 (death associated protein kinase 1)
Diseases named in the same sentence as DAPK1 in open-access papers (continued):
Sharing a sentence is not in itself a finding about the gene and the disease.
thyroid cancer (10 papers, 2013 to 2024). "DAPK1 expression was significantly associated with lower LN metastasis, suggesting its role as a potential tumor suppressor in thyroid cancer progression." (PMID 34831219, 2021). "TCGA data indicated that low-level DAPK1 is closely related to higher SI; therefore, we next investigated the association between the DAPK1 level and stemness in thyroid cancer cells." (PMID 34831219, 2021). "Compared with the control, cancer cell invasion was significantly associated with DAPK1 expression in various thyroid cancer cells in siDAPK1 of TPC-1 cells (p < 0.001)." (PMID 34831219, 2021). "This study investigated the potential role of death-associated protein kinase 1 (DAPK1) in thyroid cancer progression." (PMID 34831219, 2021). "In thyroid cancer, which is discussed in further detail later, DAPK1 is believed to have a close relationship with OCT4 (POU5F1), the master gene that controls CSC stemness." (PMID 39057063, 2024). "That study examined the mRNA expression of DAPK1 in thyroid cancer and found that the expression of DAPK1 in tumor tissue was remarkably low." (PMID 39057063, 2024). "In this review, we summarize how DAPK1 can regulate CSCs in tumor cells and influence cancer aggressiveness while focusing on thyroid cancer." (PMID 39057063, 2024). "DAPK1′s regulation of metastasis has been studied in several cancers, including colon, lung, and thyroid cancers." (PMID 39057063, 2024). "After the overexpression of DAPK1 in 8505c, MDA-T32, and TPC-1 cell lines, tumorsphere analysis (100 nm) and Aldefluor analysis at 10 days confirmed that DAPK1 was a negative regulator of thyroid cancer stemness." (PMID 39057063, 2024). "These discoveries not only provided insights into the immune-regulatory function of DAPK1 in thyroid cancer but also offered novel directions for future therapeutic strategies and exploration of immunotherapeutic targets." (PMID 38463514, 2024). "A previous thyroid cancer study indicated the mechanism by which DAPK1 regulates OCT4 (POU5F1), which is a master gene that determines CSC properties." (PMID 39057063, 2024). "A previous study on thyroid cancer reported that the hypermethylation of DAPK1 in papillary carcinoma significantly increased the aggressiveness (metastasis and lymph node metastasis) of thyroid carcinoma." (PMID 39057063, 2024). "The most well-known DAPK1-induced PTC study is a thesis reporting that the hypermethylation of DAPK1 has significant effects (metastasis, lymph node metastasis) in thyroid carcinoma." (PMID 39057063, 2024). "In conclusion, DAPK1 plays an important role as a tumor suppressor in thyroid cancer migration, invasion, and metastasis." (PMID 34831219, 2021). "In this study, we evaluated the role of DAPK1 as a regulator of cancer progression and stemness in thyroid cancer in vitro." (PMID 34831219, 2021). "We first explored the clinical importance of the DAPK1 gene in human thyroid cancer by conducting a comprehensive analysis with a transcriptome and its matched clinicopathological data in the TCGA-THCA data." (PMID 34831219, 2021). "Our findings suggest that DAPK1 is a negative regulator of cancer stemness in thyroid cancer progression by regulating Oct4 expression." (PMID 34831219, 2021). "In literature, it has been shown that the methylation status of markers like RASSF1, DAPK1, and ESR1 has been significantly associated with thyroid cancer subtypes and early detection of thyroid cancer." (PMID 32324757, 2020). "This suggested that DAPK1 could have a certain impact on regulating tumor development and immune responses in thyroid cancer, highlighting its potential significance, although the precise mechanisms require further in-depth research and validation." (PMID 38463514, 2024). "Our findings suggested that DAPK1 may play a significant role in immune regulation in thyroid cancer." (PMID 38463514, 2024).
thyroid cancer (continued). "The results of a previous study from our laboratory showed that the downregulation of DAPK1 could promote the metastatic stage of thyroid cancer." (PMID 39057063, 2024). "In the context of thyroid cancer, these activated signaling pathways might unveil the potential roles of DAPK1 in immune regulation, tumor microenvironment, and cellular behavior." (PMID 38463514, 2024). "Thus, tumorsphere formation and ALDH1 activity were also inhibited by DAPK1 in thyroid cancer cells." (PMID 34831219, 2021). "In this study, we evaluated the role of DAPK1 in thyroid cancer progression." (PMID 34831219, 2021). "This study suggested that modulating DAPK1 could be a new strategy for targeting the CSC pathway in thyroid cancer." (PMID 34831219, 2021). "However, the present study is beneficial because, for the first time, we evaluated the role of DAPK1 in regulating stemness in thyroid cancer with the validation of public data analysis." (PMID 34831219, 2021). "Consistent results were observed after KD of DAPK1 in thyroid cancer cells." (PMID 34831219, 2021). "Promoter methylation status of genes with reported associations in thyroid cancer (CASP8, CDKN2A, DAPK1, ESR1, NIS, RASSF1 and TIMP3) were examined in a cohort of follicular thyroid cancers comprising of 26 Hurthle and 27 Classic subtypes utilizing quantitative methylation-specific PCR." (PMID 27158284, 2015). "Although AUCs for DAPK1 (0.732) and RASSF1A (0.707) genes were better than other genes, the diagnostic accuracy of these two genes was still low, suggesting that these DNA methylation markers play a limited role in the diagnosis of thyroid cancer." (PMID 24588959, 2014). "Therefore, we evaluated the potential role of DAPK1 as a tumor suppressor in thyroid cancer." (PMID 34831219, 2021). "Secondly, DAPK1 may be a negative regulator of CSC-like properties in thyroid cancer." (PMID 34831219, 2021). "DAPK1 may therefore be an independent prognostic marker and therapeutic target in thyroid cancer." (PMID 34831219, 2021). "Recent studies showed that DAPK1 was involved not only in tumor suppression but also in epithelial-mesenchymal transition (EMT) and cancer stem cell (CSC) formation in colon and thyroid cancers." (PMID 39057063, 2024). "We investigated the effects of DAPK1 in thyroid cancer according to TGCA data using 8505C, MDA-T32, BCPAP, and TPC-1 cells after confirming the basal protein level of DAPK1." (PMID 34831219, 2021). "β-catenin levels increased with downregulation of DAPK1 and decreased with DAPKI overexpression in thyroid cancer cells, confirmed by confocal imaging." (PMID 34831219, 2021). "The methylation status of RASSF1, DAPK1 and ESR1 suggests the utility of methylation markers to molecularly differentiate thyroid cancer subtypes for enhanced classification and early detection of thyroid cancer." (PMID 27158284, 2015). "This indicates a close relationship of DAPK1 with the aggressiveness of PTC cancer (tumor size, lymph node metastasis, and treatment-refractory) and suggests DAPK1 as a therapeutic target and an independent prognostic marker in thyroid cancer." (PMID 39057063, 2024).
Cognitive impairment (9 papers, 2021 to 2025). Abnormal cognition is characterized by deficits in thinking, reasoning, or remembering. "Critically, either genetic ablation of DAPK1 or pharmacological inhibition of its kinase activity significantly attenuates cognitive impairment and tau-associated neuropathologies." (PMID 41272902, 2025). "Although the data from Zipk+/− mice and ZIPK knockdown cells support that partial deletion of ZIPK effectively ameliorated neuronal loss and cognitive impairment, we cannot exclude the potential contribution of DAPK1 inhibition by HS38 in the inhibitor treatment experiments." (PMID 40032841, 2025). "Elevated DAPK1 expression in hippocampal excitatory neurons correlates with cognitive deficits, increases neuronal apoptosis, and disrupts synaptic plasticity." (PMID 40787892, 2025). "The downregulation of miR-130a-3p induced by Aβ treatment promotes DAPK1 expression, resulting in accelerated neuronal cell death and cognitive impairment." (PMID 38195518, 2024). "Another report showed that DAPK1-KO prevents cognitive impairment in vascular cognitive impairment and dementia (VCID) mice." (PMID 37047515, 2023). "It has also been reported that DAPK1 promotes neuropathology after TBI, whereas suppression of both DAPK1 expression and kinase activity significantly attenuates neuronal apoptosis, synaptic loss, and cognitive impairments in TBI model mice." (PMID 37047515, 2023). "This study found that ASS could improve STZ-induced cognitive deficits in rats by regulating DAPK1 expression in hippocampal tissues and inhibiting the over-phosphorylation of the Tau protein while simultaneously reducing the expression of neuroinflammatory factors in hippocampal tissues." (PMID 40332373, 2025). "Pharmacological inhibition of DAPK1 activity attenuates the Aβ-induced NLRP3 activation and cognitive impairment in vivo." (PMID 38195518, 2024). "However, the expression of DAPK1 was significantly upregulated in the hippocampus of PS1 V97L transgenic mice compared with control mice at 6 and 9 months of age, which correlated with the appearance of Aβ accumulation and cognitive impairment." (PMID 38195518, 2024).
glioma (9 papers, 2017 to 2024). A benign or malignant brain and spinal cord tumor that arises from glial cells (astrocytes, oligodendrocytes, ependymal cells). "The role of DAPK1 (Death-associated protein kinase 1) in glioma has garnered attention for its involvement in regulating apoptosis, cell migration, and invasion." (PMID 39926603, 2024). "DAPK1’s function in glioma development is increasingly recognized as being linked to its modulation of immune responses." (PMID 39926603, 2024). "For instance, loss of DAPK1 expression in glioma cells has been associated with enhanced tumorigenicity and resistance to apoptosis, further supporting its role as a tumor suppressor." (PMID 39926603, 2024). "Dysregulated expression of DAPK1 has been associated with the invasive behavior of various malignancies, including gliomas." (PMID 39926603, 2024). "However, the precise role and underlying mechanisms of DAPK1 in gliomas remain inadequately understood." (PMID 39926603, 2024). "Additionally, DAPK1’s influence on mitochondrial dynamics and autophagic processes has been suggested to be a key mechanism underlying its ability to regulate glioma progression." (PMID 39926603, 2024). "In gliomas and glioblastoma, miR-103a-3p-DAPK1 axis and miR-22-3p-DAPK1 axis might be associated with the diagnosis and treatment of gliomas and glioblastoma." (PMID 34422899, 2021). "We conducted an investigation into the characteristics of single-cell differentiation data in gliomas, with a focus on developing DAPK1-based prognostic markers to predict patient outcomes." (PMID 39926603, 2024). "Recent studies suggest that DAPK1 can influence glioma progression through immune mechanisms, particularly by affecting immune cell infiltration and cytokine production." (PMID 39926603, 2024). "Knockdown of DAPK1 significantly inhibited glioma cell proliferation, migration, and metastatic potential, as confirmed by colony formation assays, migration assays, CCK-8 assays, and apoptosis assays." (PMID 39926603, 2024). "DAPK1-based prognostic models show promise for accurately predicting outcomes in glioblastoma and glioma." (PMID 39926603, 2024). "Together, these data suggest that DAPK1 knockdown inhibits glioma cell proliferation, migration, and enhances apoptosis, highlighting its potential role as a modulator of glioma cell survival and progression." (PMID 39926603, 2024). "In line with our results, a number of studies have reported that the downregulation of DAPK1 leads to reduced cell proliferation and migration, along with increased apoptosis, in several cancer types, including glioma." (PMID 39926603, 2024). "The findings from our functional assays underscore the critical role of DAPK1 in regulating glioma cell proliferation, migration, and apoptosis, consistent with previous studies implicating DAPK1 as a key modulator of cancer cell behavior." (PMID 39926603, 2024). "The results demonstrated that DAPK1 silencing significantly enhanced apoptosis in both U251 and LN229 glioma cell lines, indicating that the loss of DAPK1 promotes cell death in these tumor cells." (PMID 39926603, 2024). "Quantification of the migration assays revealed a significant reduction in the migratory ability of both U251 and LN229 glioma cells upon DAPK1 knockdown, supporting the notion that DAPK1 is essential for glioma cell migration." (PMID 39926603, 2024). "To explore the functional implications of DAPK1 in glioma, we conducted DAPK1 gene knockdown experiments, validating transfection efficiency through RT-qPCR." (PMID 39926603, 2024). "DAPK1 expression in glioblastomas has been demonstrated to be decreased 48, and glioma patients with high DAPK1 expression had a longer survival time according to TCGA." (PMID 35664063, 2022). "Collectively, these results reinforce the notion that DAPK1 serves as an important regulator of glioma cell survival and migration, and its downregulation may contribute to tumor aggressiveness." (PMID 39926603, 2024).
glioma (continued). "Thus, investigating DAPK1’s specific mechanisms in gliomas and its interaction with TAMs is crucial for advancing our understanding and therapeutic approaches." (PMID 39926603, 2024). "However, there is still a gap in our understanding of how DAPK1 interacts with the immune system to modulate glioma growth and treatment responses." (PMID 39926603, 2024). "The CpG site of DAPK1 is also related to the prognosis of glioma patients." (PMID 37576398, 2023). "Rapamycin promoted autophagy dependent on the miR-26a-5p/DAPK1 pathway in glioma cells." (PMID 36522638, 2022). "Targeting the DAPK1 gene may offer therapeutic benefits for glioma patients." (PMID 39926603, 2024). "Therefore, targeting DAPK1 or its downstream signaling pathways may offer promising therapeutic strategies for glioma treatment." (PMID 39926603, 2024). "However, miR-26a induced autophagy in triple-negative breast cancer cells via the MTDH pathway and miR-26a induced autophagy in glioma cells via the DAPK1 pathway, suggesting that miR-26a might indirectly inhibit autophagy." (PMID 36522638, 2022). "To investigate the role of DAPK1 in glioma cell proliferation, migration, and apoptosis, we performed a series of functional assays following DAPK1 knockdown in U251 and LN229 glioma cell lines." (PMID 39926603, 2024). "In the Glioma pathways (KEGG), 3 genes were down-regulated by both citalopram and escitalopram (E2F1, DAPK1, CCND1)." (PMID 28467792, 2017). "Colony formation assays revealed a significant reduction in colony size in the si-DAPK1 groups compared to the negative control (NC), suggesting that DAPK1 knockdown impairs the proliferative capacity of glioma cells." (PMID 39926603, 2024). "A study revealed that upregulation of DAPK1 in the peritumoral tissues can phosphorylate NR2B, which could lead to glioma-induced seizures." (PMID 34664012, 2021).
liver cancer (9 papers, 2017 to 2023). An epithelial or non-epithelial malignant neoplasm that arises from the liver. "Liver cancer with the b-catenin mutation has a lower DAPK1 expression, suggesting that DAPK1 may be regulated under the b-catenin pathway." (PMID 28740751, 2017). "As demonstrated in our China patient cohort, we found that the association between DAPK1 expression and survival was significant in liver cancer patients who had also cirrhosis implies that DAPK1 may be a potential therapeutic target for this particular group of patients." (PMID 28740751, 2017). "In liver cancer, DAPK1 expression is markedly down-regulated; low expression of DAPK1 is an unfavorable prognosis for liver cancer patients." (PMID 36290392, 2022). "Our previous study has indicated that DAPK1 and DDX20 (DEAD-box helicase 20) can suppress liver cancer cell invasion and migration, and the role of DAPK1 on the function of liver cancer depends on DDX20." (PMID 36290392, 2022). "The results showed that the expression of DAPK1 in adjacent tissues was lower than that in the liver cancer tissues." (PMID 35935258, 2022). "Previous studies reported that DAPK1 was decreased in many kinds of cancer, including lung, colon, pancreatic and liver cancers." (PMID 36290392, 2022). "DAPK1 is a tumor suppressor, and it has been reported that DAPK1 expression levels are low in liver cancer tissues (Katzenellenbogen, Baylin & Herman, 1999)." (PMID 35935258, 2022). "DAPK1 is a pro-apoptotic serine-threonine protein kinase that is downregulated in lung, colon, breast, and liver cancers." (PMID 33201837, 2020). "In conclusion, the present study has shown that DAPK1 donwregulation happens early in liver cancer development and confers poor prognosis in liver cancer patients." (PMID 28740751, 2017). "From this dataset, we found that the CTNNB1 subtype of liver cancer had a significantly lower expression of DAPK1 compared to other subtypes of liver cancer (Mann–Whitney U test, p = 0.008)." (PMID 28740751, 2017). "In view of this, immunohistochemical staining of DAPK1 was performed in 101 liver cancer specimens from 101 individual patients with various clinico-pathological parameters available." (PMID 28740751, 2017). "On the other hand, DAPK1 has been shown to be a prognostic marker in a Japanese liver cancer patient cohort with a small sample size." (PMID 28740751, 2017). "The results suggest that DAPK1 mRNA expression is a favorable prognostic marker for liver cancer patients." (PMID 28740751, 2017). "Our study aims to investigate the prognostic significance of DAPK1 in liver cancer in both mRNA and protein levels." (PMID 28740751, 2017). "As DAPK1 mRNA expression is a prognostic marker for liver cancer patients, it is interesting to also look at the prognostic significance of DAPK1 protein expression to confirm the results obtained for mRNA studies." (PMID 28740751, 2017). "The IL-8/DAPK1/lactate/regulatory T cell (Treg) axis was verified using a mouse liver cancer model." (PMID 36932390, 2023). "Bioinformatics suggests that amcinonide and sulpiride may be potential targeting agents for DAPK1 in liver cancer." (PMID 37576398, 2023). "Furthermore, reduced DAPK1 expression has been documented in renal, colorectum, and liver cancers 49-51." (PMID 35664063, 2022). "DAPK1 can inhibit the invasion and migration of liver cancer cells by up-regulating DDX20." (PMID 36290392, 2022). "However, DAPK1 is in liver cancer, especially in common liver cancer cell lines including HepG2, PLC/PRF/5, and Hep3B." (PMID 35935258, 2022). "Down-regulation of DAPK1 expression may be a prognostic factor in many tumors, such as diffuse large B-cell lymphoma and liver cancer." (PMID 34335109, 2021). "DAPK1 promoter methylation was investigated previously by others in liver cancer." (PMID 28740751, 2017).